BCR (BCR activator of RhoGEF and GTPase)
Diseases named in the same sentence as BCR in open-access papers (continued):
Sharing a sentence is not in itself a finding about the gene and the disease.
Pleural effusion (5 papers, 2021 to 2025). The presence of an excessive amount of fluid in the pleural cavity. "The TRB, TRG, and BCR IGH repertoires were characterized between the pleural effusion and blood in PLTB patients, and the shared clones were analyzed and collected." (PMID 39664375, 2024). "At 12 months, the patient achieved complete cytogenetic response (CCyR), but BCR::ABL1 levels remained suboptimal, with recurrent pleural effusion." (PMID 40166069, 2025). "After 6 months, the patient achieved partial cytogenetic response (PCyR) with BCR::ABL1 < 10%, but grade 3 pleural effusion developed." (PMID 40166069, 2025). "Dasatinib, a second-generation BCR/Abl tyrosine kinase inhibitor (TKI), has off-target effects that may contribute to adverse reactions such as PE and pleural effusion." (PMID 40862457, 2025). "Comparisons BCR–NRR (BCR/NRR-consensus agreement) and RR–NRR (RR/NRR-consensus agreement) showed lower agreement values for all pathologies (highest to lowest agreement values were: pneumothorax > pleural effusion > pneumonia > suspicious nodule)." (PMID 34679566, 2021).
Hypertension (4 papers, 2019 to 2025). The presence of chronic increased pressure in the systemic arterial system. "In the subgroup of patients with a heterogeneous BcR profile, the most observed comorbidities were hypertension (63.4%), diabetes (24.1%) and dyslipidemia (23.1%)." (PMID 40282492, 2025). "Specifically, positive associations between BCR and all-cause mortality were shown in patients of different ages, gender, AKI, hypertension, DM, heart failure, and myocardial infarction." (PMID 40110543, 2025). "Results from the PPI analysis identified IL-8, JAK2, AGTR1, and BCR to be the centers of genomic changes, in which AGTR1 was the target of hypertension, the common cause of cardiac remodeling triggered by mechanical stress." (PMID 31772688, 2019).
Immunodeficiency (4 papers, 2007 to 2023). Failure of the immune system to protect the body adequately from infection, due to the absence or insufficiency of some component process or substance. "However, defects in pre-BCR assembly and signaling may interfere with B cell development or may cause uncontrolled proliferation and genomic instability, resulting in immunodeficiency or tumor development." (PMID 23985023, 2013).
lymphoid leukemia (4 papers, 2007 to 2025). A malignant lymphocytic neoplasm of B-cell or T-cell lineage involving primarily the bone marrow and the peripheral blood. "Our data are consistent with these reports, as AICAR induced cell cycle arrest in G1-phase in all lymphoid leukemia cell lines we examined, including the BCR/ABL positive cell line SupB15." (PMID 17623090, 2007). "In the present study, we introduced the T315M mutation into the intrinsic BCR::ABL1 gene of two Ph + myeloid and one Ph + lymphoid leukemia cell lines using the CRISPR/Cas9 system to directly verify the utility of the combined asciminib and ponatinib in human models." (PMID 40208408, 2025). "This BCR-ABL SH2 domain deletion mutant renders myeloid cells lines IL-3 independent, and induces a lymphoid leukemia or a CML-like disease in mice, but the disease latency is increased as compared to full length BCR-ABL." (PMID 19823681, 2009).
meningioma (4 papers, 2015 to 2023). A generally slow growing tumor attached to the dura mater. "Similarly, the BCR gene, which typically shows lower expression in meningiomas, has also been shown to act as a negative regulator of the Wnt pathway." (PMID 28978116, 2017). "Similarly, the BCR gene, which typically shows lower expression in meningiomas with LOH at chromosome 22q, has also been shown to act as a negative regulator of the Wnt pathway." (PMID 25965831, 2015).
T-cell lymphoma (4 papers, 2014 to 2025). "Such a reduction in the level of activity could predispose an individual to late or atypical FHLH, and the development of anaplastic large cell lymphomas, B- and T-cell lymphomas and acute childhood lymphoblastic leukaemia carrying the BCR-ABL fusion gene." (PMID 24632576, 2014).
Thrombocytopenia (4 papers, 2024 to 2025). A reduction in the number of circulating thrombocytes. "The relapsed cohort exhibited distinct clinical characteristics compared to the sustained remission group, including higher proportions of intermediate- or high-risk stratification, thrombocytopenia at diagnosis, and BCR::ABL1(+)." (PMID 41488897, 2025). "Our retrospective analysis identifies thrombocytopenia at diagnosis, BCR::ABL1(+), and suboptimal early treatment response [persistent minimal residual disease (MRD)] as independent predictors of relapse." (PMID 41488897, 2025). "Independent predictors included thrombocytopenia at diagnosis (OR = 2.09, P = 0.037), BCR::ABL1(+) (OR = 3.85, P = 0.024), and positive MRD on day 19 (OR = 2.09) and day 46 (OR = 5.73, P < 0.001) of induction therapy." (PMID 41488897, 2025). "In conclusion, this study characterizes relapse patterns and prognostic determinants in pediatric ALL, highlighting the interplay among baseline thrombocytopenia, BCR::ABL1 (+) fusion gene, and MRD level." (PMID 41488897, 2025). "Thrombocytopenia at diagnosis, BCR::ABL1(+), and persistent MRD are critical relapse predictors." (PMID 41488897, 2025). "Ph+ B-ALL, defined by the presence of the BCR–ABL fusion gene, typically presents with bone marrow failure symptoms, particularly bleeding tendencies due to thrombocytopenia." (PMID 40433229, 2025). "In cases of resistance or suboptimal response, as indicatedby persistent high BCR-ABL levels or hematologic abnormalities such as neutropenia and thrombocytopenia, treatment was escalated tosecond-generation TKIs like Nilotinib or Dasatinib." (PMID 40230905, 2024).
agammaglobulinemia (3 papers, 2010 to 2024). A decreased level of serum immunoglobulins. "In summary, our analyses confirmed the pathogenicity of novel ERCC2 mutations and show that ERCC2 deficiency is associated with antibody deficiency most likely due to altered B-cell differentiation resulting from impaired BCR-mediated B-cell activation and activation-induced gene transcription." (PMID 39055713, 2024). "A prime example is the absence of peripheral blood B cells in patients with agammaglobulinemia due to mutations in BTK or related genes in the BCR signaling pathway." (PMID 31552044, 2019). "Impaired BCR mediated B-cell activation likely contributes to the antibody deficiency in TTD1 deficient patients, however it is not excluded that the previously reported defects in inborn immunity and T-cell functions might also contribute to impaired antibody production in ERCC2 deficiency." (PMID 39055713, 2024).
asthma (3 papers, 2022 to 2024). "Understanding the intricacies of early BCR activation is pivotal for delineating the mechanisms underlying IgE‐mediated asthma." (PMID 39412083, 2024). "CD22 mediated BCR regulation, heme scavenging from plasma, asthma, and antigen activates B cell receptor BCR resulting in the generation of second messengers were enriched in the low-risk group." (PMID 35991543, 2022). "In particular, seven gene targets (HMGCR, ADORA1, IL6R, CD86, BCR, PIK3CD, and NOS1) are prioritized for asthma drug repurposing." (PMID 35052792, 2022).
colorectal cancer (3 papers, 2016 to 2025). A primary or metastatic malignant neoplasm that affects the colon or rectum. "The ARID1A, BCR, CHD5, RPL22 and TSC2 genes were shared mutation targets in ovarian and colorectal carcinomas." (PMID 29296220, 2017). "For example, ZG16B, known to involve in metastasis in colorectal cancer, is potentially affected by rs9925556, and lower expression level of ZG16B that is correlated with shorter BCR-free survival in PCa." (PMID 27409348, 2016). "Furthermore, in colorectal cancer, DDR1 activates breakpoint cluster region (BCR) to sustain β-catenin transcriptional activity, a key regulator of cancer cell invasion." (PMID 40563472, 2025).
Down syndrome (3 papers, 2020 to 2025). "Only factors with a p-value of <0.2 (risk score, MRD at day 29, BCR-ABL/AF4 fusion gene and Downs Syndrome) in the univariate analysis were included in the multivariate analysis." (PMID 33134167, 2020). "Additionally, a recent study suggested that BCR signaling pathway may be involved in PD with Down syndrome." (PMID 36389665, 2022).
erythroleukemia (3 papers, 2023 to 2025). Acute erythroid leukemia characterised by the presence of at least 50% erythroid precursors and at least 20% myeloblasts in the bone marrow. "We next tried to create e13a2 type fusion in a TF-1 cell line, which is a human GM-CSF-dependent erythroleukemia cell line, since transfection of BCR::ABL1 fusion cDNA was reported to induce factor-independent cell growth." (PMID 35999358, 2023).
glioblastoma (3 papers, 2017 to 2024). The most malignant astrocytic tumor (WHO grade IV). "Patient #12, a 54-year-old male diagnosed with glioblastoma (GBM) with the BCR::NTRK2 fusion, PTEN mutation, homozygous deletion of CDKN2A/2B, and TERTp mutation (C228T), refused adjuvant therapy and received palliative care, resulting in death 13 months post-surgery." (PMID 39014476, 2024).
hypereosinophilic syndrome (3 papers, 2012 to 2025). Hypereosinophilic syndrome (HES) constitutes a rare and heterogeneous group of disorders, defined as persistent and marked blood eosinophilia and/or tissue eosinophilia associated with a wide range of clinical manifestations reflecting eosinophil-induced tissue/organ damage. "Clonal proliferation of eosinophilic leukocytes related to the Fip 1 alpha/BCR ABL mutation represents the most common form of CEL, representing the myeloproliferative subtype of the hypereosinophilic syndrome (HES)." (PMID 22348015, 2012).
liver cancer (3 papers, 2008 to 2021). An epithelial or non-epithelial malignant neoplasm that arises from the liver. "Syk, with a cancer linker degree of 17, found differentially expressed in 4 types of cancer and with a SF-Probability of 0.99, is a positive effector of BCR-stimulated responses and has been found to be involved in urinary bladder carcinoma and primary liver cancer." (PMID 18371197, 2008). "However, there is limited research on the methylation status of the BCR gene in liver cancer." (PMID 32955083, 2020).
lymphopenia (3 papers, 2017 to 2022). Reduction in the number of lymphocytes. "Flow cytometry confirmed lymphopenia and suggested basophilia, and RT-PCR established the presence of the BCR/ABL gene." (PMID 33251261, 2020). "Consistent with this notion, the SWHEL BCR, or just its (homozygous) VH10 heavy chain knock-in, led to a ~5-fold reduction of B-1a cells compared to control mice, and thereby further compounded the B-1a lymphopenia in Dynll1-deleted mice." (PMID 28922373, 2017).
Obesity (3 papers, 2021 to 2023). Accumulation of substantial excess body fat. "However, our stratified analysis suggested that the adverse effects of obesity on survival were more prominent in patients with certain risk factors, particularly B‐cell immunophenotype and BCR/ABL1 mutation." (PMID 36168702, 2023). "With regard to isorhamnetin, which has the cardiovascular and cerebrovascular protective, anti-inflammatory, anti-oxidation, organ protection, prevention of obesity, and other effects, we found that 16 isorhamnosides were more accumulated in BsR than in BcR." (PMID 35909726, 2022). "Oxytocin and APP are obesity-specific immune signaling pathways and NK-cell-mediated cytotoxicity, insulin signaling, TCR signaling, ubiquitin-mediated proteolysis, platelet activation BCR signaling, neurotrophin, and oxytocin signaling pathways are T2D immune-system-specific pathways." (PMID 33927693, 2021).
renal cell carcinoma (3 papers, 2022 to 2025). "In contrast, more than 46% of eligible patients treated with TKIs—primarily imatinib (a BCR-ABLi) and pazopanib (a VEGFi)—at the Mayo Clinic in the U.S. were mainly diagnosed with renal cell carcinoma (RCC)." (PMID 40817221, 2025).
sarcoma (3 papers, 2012 to 2024). A usually aggressive malignant neoplasm of the soft tissue or bone. "Gene fusions represent a well-established class of mutations in hematological diseases and sarcomas, with the BCR-ABL fusion in chronic myeloid leukemia and different EWS-fusions in sarcomas being prototype examples with diagnostic, prognostic and therapeutic value." (PMID 23119097, 2012). "As expected, lung tumors with driver fusions harbored mostly EML4/ALK fusions, sarcomas were driven mostly by EWSR1-related and PAX3/FOXO1 fusions, while hematologic malignancies with a spectrum of BCR/ABL1, KMT2A-related, and IGH/MYC fusions." (PMID 33889297, 2021).
Sepsis (3 papers, 2020 to 2025). Sepsis is defined as life-threatening organ dysfunction caused by a dysregulated host response to infection. "No detectable differences in either IGHV4-34 autoreactive BCR levels or class-switching were observed in sepsis cases." (PMID 35216673, 2022). "The observed autoantigen response in sepsis could be explained by a polyclonal B cell activation through PAMPs and DAMPs, which activate B cells independent of the BCR, leading to the production of the so-called NAbs, which are polyreactive." (PMID 32849533, 2020).
T-cell ALL (3 papers, 2019 to 2025). "The immunophenotypic distribution according to fusion gene status followed expected patterns, with TEL::AML1, BCR::ABL, E2A::PBX1 and MLL::AF4 fusions exclusively associated with B-cell ALL and SIL::TAL1 fusion predominantly found in T-cell ALL." (PMID 41234729, 2025). "As considered above, the BCR-ABLp210, BCR-ABLp190, and LMO2 oncogenes drive human CML, Ph+ B-cell ALL, and T-cell ALL." (PMID 35563454, 2022).
type 1 diabetes (3 papers, 2021 to 2024). "It is suggested that these “dual expressors” (DE) are increased in frequency in type 1 diabetes and that in people with type 1 diabetes there is a public BCR which can stimulate insulin-reactive CD4+ T cells." (PMID 34659258, 2021). "Patients with type I diabetes have unique TCR and BCR-positive lymphocytes." (PMID 38800484, 2024).
withdrawal syndrome (3 papers, 2024 to 2025). "In this case, the potential for withdrawal syndrome, the importance of regular BCR::ABL1 monitoring, and a quick restart of therapy should levels rise would have been key discussion points, alongside the wish of the patient to prevent ongoing side effects and to stop taking medication every day." (PMID 40161248, 2025). "Other clinical parameters were assessed, including BCR::ABL1 transcript type, withdrawal syndrome (WS), and ELTS score, which are suggested to be important in the TFR trial." (PMID 38667336, 2024). "In the univariate analysis, gender, Sokal score, type of BCR::ABL1 transcript, and withdrawal syndrome did not impact the TFR rate." (PMID 38779092, 2024).
acute kidney injury (2 papers, 2024 to 2025). Sudden and sustained deterioration of the kidney function characterized by decreased glomerular filtration rate, increased serum creatinine or oliguria. "Recent studies have shown a strong link between high BCR levels and negative clinical outcomes in various patient groups, such as those with acute kidney injury, acute decompensated heart failure, chronic heart failure, and acute myocardial infarction." (PMID 40110543, 2025).
alveolar rhabdomyosarcoma (2 papers, 2005 to 2024). A rapidly growing malignant mesenchymal neoplasm. "The BCR::ABL1-positive CML cell line KCL-22 and the rhabdomyosarcoma cell line HTB-153 express SLC22A5 mRNA at comparable levels." (PMID 39182842, 2024).
atherosclerosis (2 papers, 2023 to 2025). A disease characterized by the build-up of fatty material and calcium deposition in the arterial wall resulting in partial or complete occlusion of the arterial lumen. "These DEGs and pathway analyses suggested that BCR signaling may be enriched in patients with severe atherosclerosis." (PMID 38259450, 2023). "In ABC CD11c+ B cells, DEG and IPA suggested that BCR signalling may be enriched in cells from patients with severe atherosclerosis, as exemplified by higher expression of Itgax (CD11c), a marker of activation, and lower expression of Cd72, an inhibitor of BCR signalling." (PMID 40497946, 2025).
bladder cancer (2 papers, 2008 to 2021). "Although there were reports of structural features in the BCR region of ABL1, VNTR was not reported in previous studies, so this study focused on the association between VNTR in the BCR region and bladder cancer." (PMID 33952249, 2021). "In particular, an association with bladder cancer in the BCR region of ABL1 has also been reported." (PMID 33952249, 2021).
childhood cancer (2 papers, 2023). "One childhood cancer survivor had her first autotransplantation in 2017 prior to receiving a negative result of BCR-ALB transcript in analyzed OT." (PMID 37686475, 2023).
depression (2 papers, 2020 to 2023). "In this analysis, similar factors such as BCR or anxiety and depression symptoms showed associations with increased levels of fear of cancer recurrence." (PMID 36254563, 2023). "It is reported that rs131702 of BCR in Japanese patients are related to bipolar II depression characterized by fluctuation between abnormal mood states of mania and depression." (PMID 32747715, 2020). "Our results indicate that rs131702 of BCR is independent of depression in this study and is, therefore, a prognostic factor unique to tinnitus." (PMID 32747715, 2020).
hepatorenal syndrome (2 papers, 2024 to 2025). Hepatorenal syndrome is a form of impaired kidney function that occurs in individuals with advanced chronic liver disease. "Renal insufficiency occurs in about 20% of patients with cirrhosis, and fluctuations in creatinine in these patients are closely related to hepatic and renal impairment, and an elevated BCR may imply reduced hepatic metabolic function and impaired renal perfusion." (PMID 40110543, 2025).
Lymphadenopathy (2 papers, 2015 to 2025). Enlargement (swelling) of a lymph node. "The aim of this study was to elucidate the possible role of impaired egress as a determinant of lymphadenopathy in CLL, and relief of impaired egress as an explanation for the mobilizing effect of BCR signaling pathway inhibitors." (PMID 25632006, 2015).
lymphoproliferative disorder (2 papers, 2014 to 2023). "We have previously observed that in MCL, another lymphoproliferative disorder characterized by a strong dependence on the microenvironment, the stabilization of β-catenin upon BCR stimulation is associated with BTK activity." (PMID 38139452, 2023). "In fact, our discovery may be of fundamental biological significance as PLCγ2 is a critical signaling regulator of B-cell activation, whose hypoactivation could be used as a biomarker for response to therapies targeting the BCR signaling pathway, in CLL and other lymphoproliferative disorders." (PMID 24489640, 2014).
metastatic disease (2 papers, 2012 to 2022). "There was a trend for mean times to BCR (P = 0.081), and metastatic disease (P = 0.060), to be different between pT2/margin negative patients and pT3/margin positive patients." (PMID 21941534, 2012).
myeloid sarcoma (2 papers, 2020 to 2025). A tumor mass composed of myeloblasts or immature myeloid cells. "CP-CML is defined by the presence of the BCR::ABL1 fusion gene, while BP-CML is diagnosed when blasts in peripheral blood (PB) or bone marrow (BM) exceed ≥20%, or when myeloid sarcoma or lymphoblast infiltration is present." (PMID 40507313, 2025).
myocardial infarction (2 papers, 2023 to 2025). Gross necrosis of the myocardium, as a result of interruption of the blood supply to the area, as in coronary thrombosis. "One of the three patients with a BCR::ABL1 mutation had a myocardial infarction prior to the start of TKI." (PMID 37444494, 2023).